CFTR (CF transmembrane conductance regulator)
Diseases named in the same sentence as CFTR in open-access papers (continued):
Sharing a sentence is not in itself a finding about the gene and the disease.
cystic fibrosis (continued). "One female candidate dropped out after the first appointment dueto ongoing pregnancy.Thirty-four males and 63 females performed karyotype and screening for the morecommon pathogenic variants for SMA and CFTR-related cysticfibrosis." (PMID 35916466, 2022). "Cystic fibrosis, caused by loss of function mutations in the CFTR gene, is the most common life-limiting genetic disease in populations of European descent, affecting one in ∼2500 to 3000 newborns." (PMID 35065958, 2022). "The chloride channel dysfunction caused by deleterious cystic fibrosis transmembrane conductance regulator (CFTR) variants generally correlates with severity of cystic fibrosis." (PMID 35315358, 2022). "To date, more than 2000 CFTR variants including 383 CF-causing mutations have been reported (“Cystic Fibrosis Mutation Database,” 2021)." (PMID 35813815, 2022). "Cystic fibrosis is due to deleterious alterations in both alleles coding for the cystic fibrosis transmembrane conductance regulator (CFTR)." (PMID 36140794, 2022). "Mutations in the CFTR anion channel cause cystic fibrosis and have also been related to higher cancer incidence." (PMID 35500936, 2022). "Cystic fibrosis is a multisystemic life-limiting autosomal recessive genetic disease caused by a defect in the CF transmembrane conductance regulator (CFTR) gene." (PMID 36554044, 2022). "For example, 14-3-3 proteins are positive regulators of the chloride channel cystic fibrosis transmembrane conductance regulator (CFTR), whose F508del mutation is frequent cause of cystic fibrosis." (PMID 36188227, 2022). "Cystic fibrosis is a genetic disease caused by mutation of the CFTR gene, which encodes a chloride and bicarbonate transporter in epithelial cells." (PMID 36293229, 2022). "Deletion of phenylalanine 508 (F508del) in the cystic fibrosis transmembrane conductance regulator (CFTR) anion channel is the most common cause of cystic fibrosis." (PMID 35065958, 2022). "Severe CFTR mutations that diminish chloride conductance cause cystic fibrosis if both alleles are affected, whereas heterozygous carrier status increases risk for chronic pancreatitis (CP)." (PMID 36264955, 2022). "Cystic fibrosis is the most common inherited disease in the Caucasian population, caused by mutations in the CF transmembrane conductance regulator (CFTR) gene." (PMID 35465025, 2022). "Cystic fibrosis is a life-limiting genetic disease resulting from mutations in the CF transmembrane conductance regulator (CFTR) gene." (PMID 35072004, 2022). "Cystic Fibrosis is a monogenic recessive disease caused by mutations in the cystic fibrosis transmembrane conductance (CFTR) gene." (PMID 35292885, 2022). "Small molecule modulators of CFTR are thus highly promising therapeutic interventions for patients with cystic fibrosis, particularly those expressing the ΔF508 mutation." (PMID 36093106, 2022). "Cystic fibrosis is a progressive, autosomal recessive disease caused by mutations in the cystic fibrosis transmembrane conductance regulator (CFTR) gene." (PMID 34986321, 2022). "Cystic fibrosis, due to pathogenic variants in CFTR gene, is associated with chronic infection/inflammation responsible for airway epithelium alteration and lung function decline." (PMID 35372502, 2022). "Cystic fibrosis is caused by CFTR (cystic fibrosis transmembrane regulator) mutations, which lead to dysfunction in the chloride channel and induce mucus hypersecretion and impaired mucociliary clearance." (PMID 35174108, 2022). "Cystic Fibrosis is a monogenic disease caused by mutations in the CFTR gene encoding for the cystic fibrosis transmembrane conductance regulator (CFTR) protein." (PMID 35743652, 2022). "Cystic fibrosis is caused by genetic defects that impair the CFTR channel in airway epithelial cells." (PMID 35922154, 2022). "Cystic fibrosis is a fatal inherited disease caused by mutations in CFTR that lead to varying clinical manifestations and severity." (PMID 35269585, 2022).
cystic fibrosis (continued). "The presence of complex alleles in the CFTR gene can lead to difficulties in diagnosing cystic fibrosis and cause resistance to therapy with CFTR modulators." (PMID 36286063, 2022). "Cystic fibrosis is a common hereditary autosomal recessive disease in the Caucasian population, the molecular cause of which are mutations in the CFTR gene." (PMID 35365085, 2022). "In humans, mutations in the CFTR gene cause cystic fibrosis, which is characterized by defective electrolyte and fluid transport in many different epithelia and has been long observed with fertility problems in both men and women." (PMID 36101387, 2022). "Mutations in the CFTR gene lead to Cystic Fibrosis —the most common lethal and life-limiting autosomic recessive disease among the Caucasian population." (PMID 35892592, 2022). "Cystic Fibrosis is a genetic syndrome characterized by mutations in the CF transmembrane conductance regulator gene." (PMID 35251008, 2022). "Cystic fibrosis results from nucleotide alterations in the cystic fibrosis transmembrane conductance regulator (CFTR) gene, which encodes an ATP-binding cassette transporter that functions as an ATP-gated anion channel in epithelial tissues." (PMID 35315358, 2022). "Cystic fibrosis is a heterogeneous multiorgan disease caused by mutations in a gene that leads to a defective or missing CF transmembrane conductance regulator." (PMID 36186778, 2022). "Cystic fibrosis is a genetic disease affecting over 70,000 people globally and caused by mutations in the cystic fibrosis transmembrane regulator (CFTR) gene." (PMID 36012518, 2022). "Our study indicates that ICSI in couples with very severe oligozoospermia can lead to an increase in children at risk for cystic fibrosis if both parties carry the CFTR gene mutation." (PMID 35646184, 2022). "Cystic fibrosis is a fatal hereditary condition caused by mutations in the cystic fibrosis conductance regulator (CFTR) gene." (PMID 35392868, 2022). "In combination with CFTR correctors, which traffic F508del‐CFTR to the plasma membrane, ivacaftor also has clinical benefit for cystic fibrosis patients with the predominant F508del variant." (PMID 34644413, 2022). "Cystic fibrosis is a common hereditary autosomal recessive disease caused by pathogenic variants of the CFTR gene." (PMID 36286063, 2022). "In the cohort of Russian patients with cystic fibrosis, the p.[Leu467Phe;Phe508del] complex allele (legacy name [L467F;F508del]) of the CFTR gene is understudied." (PMID 36142302, 2022). "Cystic fibrosis is a monogenic disease caused by pathogenic variants of the CFTR gene, encoding a cAMP/PKA-activated chloride channel, with multifaceted phenotypical manifestations." (PMID 35462606, 2022). "Diagnostic alternatives are detection of two cystic fibrosis-related mutations and CFTR functional tests." (PMID 36006942, 2022). "They maintain the fluid and mucus physiology of the airways and are a major source of CFTR activity (mutations of CFTR are the most common cause of cystic fibrosis)." (PMID 36402755, 2022). "The F508del mutation in nucleotide-binding domain-1 (NBD1) of the cystic fibrosis transmembrane conductance regulator (CFTR) is the predominant cause of cystic fibrosis." (PMID 36291643, 2022). "Another role of SLC9A3 as an important interacting partner or modifier of the cystic fibrosis transmembrane conductance regulator (CFTR), a gene of which mutations are causative for cystic fibrosis, has been described recently." (PMID 35239655, 2022). "NGS sequencing revealed cystic fibrosis in three patients and detected heterozygous CFTR variants in 11 patients (ten CFTR-RD variants, one CF causing variant)." (PMID 35626323, 2022). "Cystic fibrosis is a autosomal recessive, multisystemic disease caused by different mutations in the CFTR gene encoding CF transmembrane conductance regulator." (PMID 36670555, 2022).
cystic fibrosis (continued). "Since the CFTR gene was first described in 1989, 2107 variants have been reported in the cystic fibrosis mutation database, of which 431 are associated with the risk of disease." (PMID 35698092, 2022). "Loss-of-function mutations of the CFTR gene cause cystic fibrosis through a variety of molecular mechanisms involving altered expression, trafficking, and/or activity of the CFTR chloride channel." (PMID 35328596, 2022). "Approximately 10% of the cystic fibrosis population have at least one CFTR allele with a nonsense mutation that generates a nonsense codon (premature termination codon) in the mRNA4–6." (PMID 35487895, 2022). "Cystic fibrosis is a life-threatening genetic disease caused by mutations in the gene encoding cystic fibrosis transmembrane conductance regulator (CFTR)." (PMID 36108062, 2022). "Cystic fibrosis, an autosomal recessive monogenetic disorder, is caused by mutations in the CF transmembrane conductance regulator (CFTR) gene on chromosome 7." (PMID 36437445, 2022). "The inclusion of CFTR is simply to provide an additional example where a TE variant near a target gene is associated with a disease trait in humans (e.g. cystic fibrosis)." (PMID 35413944, 2022). "Cystic fibrosis is a multi-organ recessive genetic disorder caused by mutations in the CFTR (CF transmembrane conductance regulator) gene." (PMID 35163362, 2022). "Cystic fibrosis, which is the most common inherited genetically determined disease caused by a mutation in the gene for the CF transmembrane conductance regulator protein." (PMID 36313742, 2022). "Homozygous or compound heterozygous reduced function variants in CFTR are the known cause of cystic fibrosis and somatic CFTR mutations are enriched in non-small cell lung cancer." (PMID 35715537, 2022). "Cystic fibrosis is an autosomal recessive disorder caused by mutations in the CF transmembrane conductance regulator (CFTR) gene which is located on the long arm of chromosome 7." (PMID 36517903, 2022). "Cystic fibrosis is an autosomal recessive monogenic disease caused by mutations in the cystic fibrosis transmembrane conductance regulator (CFTR) gene which is located on chromosome 7q31.2 and was discovered in 1989." (PMID 34415821, 2022). "Such diseases include cystic fibrosis, which is the most common inherited genetically determined disease caused by a mutation in the gene for the CF transmembrane conductance regulator protein." (PMID 36271282, 2022). "Cystic fibrosis is a recessive genetic disease in which mutations of the CF transmembrane conductance regulator (CFTR) gene result in a multi-systemic disorder." (PMID 36312921, 2022). "Lumacaftor/ivacaftor (LUMA-IVA) therapy is prescribed to people with cystic fibrosis (pwCF) homozygous for the Phe508del-CFTR variant to restore CFTR protein function." (PMID 35207740, 2022). "Hundreds of mutations in the gene CFTR lead to cystic fibrosis and represent a challenge to developing therapeutics." (PMID 35906215, 2022). "Cystic fibrosis is an autosomal recessive genetic disease caused by mutations in the CF transmembrane conductance regulator (CFTR) gene." (PMID 35017302, 2022). "Mutations in the chloride channel CFTR that impair plasma membrane insertion and ion transport are the cause of cystic fibrosis." (PMID 35739107, 2022). "Cystic fibrosis is generally considered to be a genetic disease caused by mutations in the CF transmembrane conduction regulator (CFTR) gene." (PMID 36278189, 2022). "Cystic fibrosis is a common genetic disease caused by mutations in the gene that encodes the cystic fibrosis transmembrane conductance regulator (CFTR)." (PMID 36264792, 2022). "Cystic fibrosis is an autosomal recessive multi-organ disease caused by mutations in the cystic fibrosis transmembrane conductance regulator (CFTR) gene." (PMID 36293733, 2022).
cystic fibrosis (continued). "Cystic fibrosis is caused by a mutation of the cystic fibrosis transmembrane regulator (CFTR) gene on the long arm of chromosome 7, which encodes the CFTR protein." (PMID 36628032, 2022). "Cystic fibrosis is a life-threatening autosomal-recessive disease caused by mutations in a single gene encoding cystic fibrosis transmembrane conductance regulator (CFTR)." (PMID 36304167, 2022). "Mutations in the CFTR chloride channel result in intestinal obstructive episodes in cystic fibrosis patients and in CF animal models." (PMID 36077390, 2022). "Cystic Fibrosis is a disease caused by mutations in the CFTR gene that severely affects the lungs as well as extra-pulmonary tissues, including the gastrointestinal (GI) tract." (PMID 35743652, 2022). "Ivacaftor (VX-770) is the first CFTR potentiators approved by the FDA for cystic fibrosis patients with the gated mutation." (PMID 35773269, 2022). "Deletion of phenylalanine 508 (∆F508) of the Cystic Fibrosis Transmembrane Conductance Regulator (CFTR) anion channel protein is the leading cause of Cystic Fibrosis." (PMID 35269585, 2022). "More than 2,100 pathogenic, probably pathogenic, benign, and of unclear clinical significance sequence variants of the CFTR gene are registered in Cystic Fibrosis Mutation Database (CFTR1)." (PMID 35365085, 2022). "Cystic fibrosis is a lethal hereditary disease caused by loss-of-function mutations of the chloride channel cystic fibrosis transmembrane conductance regulator (CFTR)." (PMID 35813815, 2022). "This short report documented cystic fibrosis transmembrane conductance regulator (CFTR) variants in 37 patients with cystic fibrosis in the Rio Grande do Norte region of Northeast Brazil." (PMID 36369753, 2022). "For instance, VX-809 (lumacaftor) and the newest VX-661 (tezacaftor) have been approved by FDA as pharmacological chaperones for the treatment of cystic fibrosis, acting on the F508del mutation of CFTR associated with protein misfolding." (PMID 36034862, 2022). "Cystic fibrosis is an inborn genetic disorder caused by mutations in the cystic fibrosis transmembrane conductance regulator (CFTR) gene, which impair its function to regulate a chloride ion channel and fluid secretion across epithelial cell membranes." (PMID 36361933, 2022). "In particular, congenital bilateral absence of the vas deferens (CBAVD) represents a minor variant of cystic fibrosis and results from mutations in the CF transmembrane conductance regulator (CFTR) gene." (PMID 35349114, 2022). "Most cases of cystic fibrosis are caused by class 2 mutations in the cystic fibrosis transmembrane regulator (CFTR)." (PMID 35302062, 2022). "This defense mechanism is altered in people with cystic fibrosis, a lethal automosal recessive genetic disease caused by mutations of the CF transmembrane conductance regulator (CFTR) gene encoding the CFTR chloride channel." (PMID 35563895, 2022). "Cystic fibrosis is the most frequent life-threatening genetic disease among Caucasians and is caused by mutations in the CF Transmembrane Conductance Regulator (CFTR) gene." (PMID 36009545, 2022). "In our study, it was offered standard genetic counseling and basic carrier screening,studying pathogenic variants for SMA and CFTR-related cysticfibrosis, karyotype, FMR1 in females, and performing hemoglobinelectrophoresis in some candidates." (PMID 35916466, 2022). "Cystic fibrosis is a genetic disease arising from mutations in the cystic fibrosis transmembrane conductance regulator (CFTR) gene that causes defective chloride secretion." (PMID 36000724, 2022). "Cystic fibrosis is a genetic disease that is difficult to treat and caused by dysfunction of the cystic fibrosis transmembrane conductance regulator (CFTR) protein." (PMID 35844763, 2022). "Mutations in the cystic fibrosis transmembrane conductance regulator (CFTR) gene cause cystic fibrosis, the most common life-threatening monogenic disease among Caucasians." (PMID 36232697, 2022).
cystic fibrosis (continued). "Cystic Fibrosis is caused by a diverse set of mutations distributed across the approximately 250 thousand base pairs of the CFTR gene locus, of which at least 382 are disease-causing (CFTR2.org)." (PMID 35330693, 2022). "Cystic fibrosis is an autosomal recessive chronic disease caused by mutations in the cystic fibrosis transmembrane conductance regulator (CFTR) gene that alter its synthesis, processing, and function." (PMID 36145554, 2022). "CFTR-modulators are a category of drugs that facilitate trafficking and opening of the abnormal CFTR protein in individuals with cystic fibrosis who have certain genetic mutations." (PMID 35062937, 2022). "Cystic fibrosis, the most common lethal autosomal recessive disorder in Caucasian populations, is a multisystem condition caused by mutations in the CF transmembrane conductance regulator (CFTR) gene." (PMID 34994881, 2022). "Previous studies reported the influence of cis variants in F508del cystic fibrosis patients in their responses to CFTR modulators." (PMID 36143206, 2022). "Cystic fibrosis is a genetic condition of autosomal recessive inheritance related to mutations in the gene coding for the cystic fibrosis transmembrane conductance regulator (CFTR) protein." (PMID 35276841, 2022). "At the same time, the Cystic Fibrosis Genetic Analysis Consortium records over 2100 mutations in the CFTR gene, whereas 66% of all mutations are F508del." (PMID 35409752, 2022). "LNP-carrying chemically modified IVT-mRNA encoding cystic fibrosis transmembrane conductance regulator (CFTR) was successfully applied for the treatment of cystic fibrosis following nasal administration in CFTR knockout mice." (PMID 35055244, 2022). "Cystic fibrosis is a monogenetic autosomal recessive disorder caused by loss-of-function mutations in the cystic fibrosis transmembrane conductance regulator (CFTR) gene." (PMID 35487895, 2022). "Based on an extended DNA analysis, we can detect not only cystic fibrosis patients but also mutated gene carriers, patients with CFTR-dependent diseases, and children with CFSPID." (PMID 36364923, 2022). "The genetic disease cystic fibrosis is caused by mutations in the CF transmembrane conductance regulator (CFTR) protein." (PMID 35756994, 2022). "Cystic fibrosis is an autosomal recessive disorder caused by mutations in the cystic fibrosis transmembrane conductance regulator (CFTR) that can lead to terminal respiratory failure." (PMID 35995803, 2022). "Cystic fibrosis is an autosomal recessive disease caused by mutations in the Cystic Fibrosis Transmembrane Receptor (CFTR) gene." (PMID 36498475, 2022). "Cystic fibrosis is an autosomal recessive disease caused by mutations of the Cystic Fibrosis Transmembrane Conductance Regulator (CFTR) gene, located on chromosome 7." (PMID 36360546, 2022). "The genetic disease cystic fibrosis results when mutations in the gene for the anion channel CFTR reduce CFTR’s activity below a critical level." (PMID 35312728, 2022). "Ivacaftor was the first drug to target the root cause of cystic fibrosis, pathogenic variants in the cystic fibrosis transmembrane conductance regulator (CFTR)." (PMID 34644413, 2022). "Cystic fibrosis, a recessive genetic disease with a single gene mutation, is caused by dysfunction of the CF transmembrane conductance regulator (CFTR)." (PMID 35343091, 2022). "Cystic Fibrosis is an autosomal recessive disease caused by mutations in the gene encoding for the Cystic Fibrosis Transmembrane Conductance Regulator (CFTR) protein." (PMID 35406809, 2022). "The predominant mutation causing cystic fibrosis, the deletion of phenylalanine 508 (Δ508) in the cystic fibrosis transmembrane conductance regulator (CFTR), leads to severe defects in CFTR biogenesis and function." (PMID 36264792, 2022). "Cystic fibrosis is a life-shortening multisystemic monogenetic disease caused by mutations in the cystic fibrosis transmembrane conductance regulator (CFTR) gene." (PMID 35204878, 2022).